BARD1 (BRCA1 associated RING domain 1)
Diseases named in the same sentence as BARD1 in open-access papers (continued):
Sharing a sentence is not in itself a finding about the gene and the disease.
hereditary cancer (12 papers, 2014 to 2024). Malignant neoplasms occurring in families at a rate greater than that expected by chance and caused by germline mutations in a specific gene. "Although risk estimates for developing cancer in carriers of BARD1 variants remains to be validated for clinical settings, BARD1 has been included in multi-gene testing panels in hereditary cancer medical genetic settings." (PMID 32726901, 2020). "Pathogenic TE insertions are associated with various hereditary cancers, including hereditary breast and ovarian cancer syndrome (BRCA1, BRCA2, and BARD1); Lynch syndrome (MLH1); and colorectal cancer (APC)." (PMID 39697868, 2024). "Unexpectedly, germline genetic analysis of the rest of 84 genes included in the SOPHIA Hereditary Cancer Solution revealed the presence of a heterozygous deletion of exons 8–11 in BARD1 gene (NM_000465.2)." (PMID 36709314, 2023). "A comprehensive BARD1 screening by multigene panel analysis was performed in 4015 unrelated patients according to our regional guidelines for genetic testing in hereditary cancer." (PMID 33498765, 2021).
prostate carcinoma (12 papers, 2015 to 2025). A carcinoma that arises from epithelial cells of the prostate gland. "Taken together, these data indicate that PALB2 or BARD1 loss in prostate cancer cells is sufficient to induce an HR-deficient phenotype." (PMID 35768576, 2022). "Here, using a series of prostate cancer cell lines, we show that PALB2 or BARD1 loss is sufficient to induce an HR-deficient phenotype and sensitize prostate cancer cells to PARP inhibition." (PMID 35768576, 2022). "We also genotyped 5715 men with unselected prostate cancer, and 10,252 controls for three recurrent BARD1 variants, including p.Q564X, p.R658C and p.R659=." (PMID 34771627, 2021). "A synonymous variant p.R659= of BARD1 was detected in 19 (0.33%) men with unselected prostate cancer and in 35 (0.34%) cancer-free controls (OR = 0.97, p = 0.93)." (PMID 34771627, 2021). "A truncating BARD1 mutation p.Q564X was detected in 7 (0.12%) men with prostate cancer compared to 15 (0.15%) cancer-free individuals (OR = 0.84, p = 0.87)." (PMID 34771627, 2021). "Our study is the first to evaluate the association between BARD1 mutations and prostate cancer susceptibility." (PMID 34771627, 2021). "In a large study of 5545 European-ancestry men with prostate cancer, only nine (0.16%) patients carried a BARD1 mutation (six different BARD1 mutations)." (PMID 34771627, 2021). "To establish if BARD1 mutations also predispose to prostate cancer, we screened BARD1 in 390 Polish patients with hereditary prostate cancer." (PMID 34771627, 2021). "In the event that a BARD1 mutation is found, the men will wish to know if they face an elevated risk for prostate cancer." (PMID 34771627, 2021). "A missense variant p.R658C of BARD1 was detected in 39 (0.68%) unselected prostate cancer cases compared to 61 (0.60%) cancer-free controls (OR = 1.15, p = 0.57)." (PMID 34771627, 2021). "This study is the first to evaluate the role of BARD1 in genetic susceptibility to prostate cancer." (PMID 34771627, 2021). "To establish whether BARD1 mutations predispose to prostate cancer, we sequenced BARD1 in 390 hereditary prostate cancer cases, genotyped 5715 men with unselected prostate cancer and 10,252 controls for three recurrent rare BARD1 variants in Poland." (PMID 34771627, 2021). "Because BRCA1 is a prostate cancer susceptibility gene (with an estimated risk for prostate cancer of two- to four-fold by the age of 65), and the BRCA1 protein interacts with the BARD1 protein, we considered BARD1 to be a candidate prostate cancer susceptibility gene." (PMID 34771627, 2021). "However, while control (siNEG) cells form Rad51 foci indicative of HR-mediated repair, cells with siRNA-mediated depletion of PALB2 or BARD1 resemble BRCA2-deficient cells and fail to form Rad51 foci, suggesting that PALB2 or BARD1 loss is sufficient to confer HR deficiency in prostate cancer cells." (PMID 35768576, 2022). "A similar observation was made regarding the family history of prostate cancer, which was present in 25% of BARD1 carriers compared to only 2.4% of BRCA1 carriers (p-value = 0.005)." (PMID 40805222, 2025). "The Food and Drug Administration has approved PARP inhibitors to treat metastatic prostate cancer patients with DNA repair deficiencies due to pathogenic variants in genes involved in homologous recombination repair (HRR), including BARD1." (PMID 40805222, 2025). "BARD1 loss is sufficient to confer an HRD phenotype and significantly increase sensitivity to PARP inhibitors in prostate cancer cells." (PMID 37193789, 2023). "Here we use a combination of functional approaches to demonstrate that loss of PALB2 or BARD1 is sufficient to confer an HR-deficient phenotype and drive PARP inhibitor sensitivity in prostate cancer models." (PMID 35768576, 2022). "We used functional approaches to directly test the impact of PALB2 and BARD1 loss on homologous recombination (HR) function and PARP inhibitor sensitivity in prostate cancer cell lines." (PMID 35768576, 2022).
prostate carcinoma (continued). "PALB2 or BARD1 loss also significantly increased sensitivity to the PARP inhibitors olaparib and rucaparib across a panel of prostate cancer cell lines." (PMID 35768576, 2022). "We tested the impact of PALB2 or BARD1 loss on olaparib and rucaparib sensitivity across prostate cancer cell lines and observed a significant increase in sensitivity in PALB2- or BARD1-depleted cells compared to control cells across the cell line models." (PMID 35768576, 2022). "First, we fully sequenced the BARD1 gene in 390 Polish patients from families with hereditary prostate cancer." (PMID 34771627, 2021). "We first assessed the frequency of PALB2 and BARD1 alterations in advanced prostate cancer." (PMID 35768576, 2022). "Therefore, to gain additional insights regarding the role of PALB2 and BARD1 alterations on prostate tumor biology and therapy response, we modeled PALB2 and BARD1 loss in the prostate cancer cell lines DU145, LNCaP, and 22Rv1." (PMID 35768576, 2022). "It is not justified to inform men about increased prostate cancer risk in case of identification of a BARD1 mutation." (PMID 34771627, 2021). "Our results that BARD1 mutations do not confer increased risk of prostate cancer are in line with several previous reports." (PMID 34771627, 2021). "In a study from the UK of 1281 early-onset cases and 1160 selected controls, no pathogenic for prostate cancer BARD1 mutations were reported." (PMID 34771627, 2021). "It is not justified to inform men about increased prostate cancer risk in case of identification of a BARD1 mutation using currently existing comprehensive gene testing panels." (PMID 34771627, 2021). "In the current study, we did not observe an increased risk for prostate cancer given any of the three BARD1 variants studied." (PMID 34771627, 2021). "We also showed that these variants (including a truncating BARD1 mutation) did not influence prostate cancer characteristics or survival among the carriers." (PMID 34771627, 2021). "We sequenced the BARD1 gene in 390 Polish men with hereditary prostate cancer." (PMID 34771627, 2021). "Neither of the other two variants of the BARD1 gene, a missense substitution p.R658C and a synonymous change p.R659=, were associated with elevated prostate cancer risk." (PMID 34771627, 2021). "There are no studies to date which reported the influence of BARD1 mutations on prostate cancer risk." (PMID 34771627, 2021). "Then, we analyzed clinical characteristics of patients with prostate cancer who carried BARD1 p.Q564X truncating mutation to those in non-carriers." (PMID 34771627, 2021). "No mutations were detected in BARD1 by Invitae by sequencing in 140 African-American patients with prostate cancer and 1695 Caucasian American men with prostate cancer." (PMID 34771627, 2021). "In aggregate, our study suggests that BARD1 mutations do not predispose to prostate cancer." (PMID 34771627, 2021). "We conclude that men with a BARD1 mutation are not at elevated prostate cancer risk." (PMID 34771627, 2021). "The prostate cancer case also had P/LPGVs in BARD1, NF2, and POLE, all of which were not reported on the TGP." (PMID 41465149, 2025). "In several tumor types, particularly breast, ovarian, pancreatic, and prostate cancers, a strong correlation was observed between increased gLOH and biallelic alterations in other HR genes beyond BRCA1 and BRCA2, including BARD1, PALB2, FANCC, RAD51C, and RAD51D." (PMID 37761329, 2023). "Moreover, there is good evidence from prostate cancer that the PARPi olaparib is effective in tumours with alterations in RAD51C, RAD51D, CHEK2, PALB2, RAD54L, and BARD1." (PMID 34680387, 2021). "Finally, we did not observe LOH at the BARD1 locus in prostate cancers." (PMID 34771627, 2021).
breast and ovarian cancer (9 papers, 2014 to 2026). "Loss of BARD1 has been linked to increased susceptibility to hereditary breast and ovarian cancer (HBOC) and is associated with loss of tumor suppressor activity." (PMID 30925164, 2019). "In conclusion, we detected a significantly high prevalence of PALB2, BARD1, and BLM mutations, with a low frequency of mutant CHEK2 in the current Japanese cohort of 568 patients with BRCA1/2 WT HBOC syndrome." (PMID 32566746, 2020).
colon cancer (8 papers, 2013 to 2025). "BRCA1-associated RING domain protein 1 (BARD1) splice variant (SV), BARD1β, can sensitize colon cancer cells to poly ADP ribose polymerase 1 (PARP-1) inhibition by impairing BRCA1 mediated DNA homologous recombination repair." (PMID 32010626, 2019). "Finally, a significant association found between over-expression of FL BARD1 and favorable outcome in colon cancer patients highlighted FL BARD1 function as prognostic factor in cancer." (PMID 29292755, 2017). "We previously reported association of loss of full-length (FL) BARD1 with poor prognosis in colon cancer as well as expression of various BARD1 SVs with unknown function." (PMID 27197561, 2016). "Consistently, FL BARD1 was observed to be down-regulated not only in leukemia, but also in colon cancer patients and NSCLC samples." (PMID 24349422, 2013). "Typically in colon cancer, BRCA1 is wild type, but we have reported that FL BARD1 expression may be lost, which is associated with poorer outcome." (PMID 27197561, 2016). "Although colon cancer cells usually express wild type BRCA1, presence of an oncogenic BARD1 splice variant (SV) in select cancers may render BRCA1 dysfunctional and allow cells to become sensitive to HR targeting therapies." (PMID 27197561, 2016). "As the role of BRCA1/BARD1 in DDR might be ubiquitous and significant to different cell lines, such as neurons and colon cancer cells, the model proposed here might be relevant to different cellular backgrounds." (PMID 29180510, 2018). "Interestingly, the absence of BARD1 due to promoter methylation was observed only once, in a series of colon cancers." (PMID 33530592, 2021).
breast tumors (7 papers, 2020 to 2024). "To study mechanisms of PARPi resistance in-vivo, we isolated Brca1- or Bard1-deficient breast tumor cells (hereafter referred to as “Brca1-def” and “Bard1-def”) derived from Brca1- or Bard1-conditionally deleted mice and injected these cells in the mammary glands of syngeneic B6/129F1 mice." (PMID 38956205, 2024). "In contrast to the well-established PARPi-resistance mechanisms based on restoration of BRCA1/2 pathway functions, we identify an adaptive mechanism driven by PGF-FLT1-AKT signaling that protects Brca1- and Bard1-deficient breast tumor cells from PARPi-induced cell death in-vivo." (PMID 38956205, 2024).
cervical cancer (7 papers, 2011 to 2025). A primary or metastatic malignant neoplasm involving the cervix. "BARD1 mutation carriers were more likely to have a family history of liver, prostate, and cervical cancers (p-values = 0.004, 0.018, and 0.037, respectively) than patients who tested negative for mutations." (PMID 40805222, 2025). "Mutations in BARD1 have been associated with susceptibility to various cancers, including lung, breast, and cervical cancers." (PMID 37727789, 2023). "In addition, other studies have reported different BARD1 mutations linked to various gynecological cancers such as fallopian tubes, ovarian, and cervical cancers involving c.1977A > G, p.Gln715Ter, c.2148delCA, and p.Thr716fs*12." (PMID 35650591, 2022). "BARD1 mutation carriers in our study were more likely to have a family history of liver, prostate, and cervical cancers than patients who tested negative for the 30 gene panel (p-values = 0.04, 0.018, and 0.037, respectively)." (PMID 40805222, 2025). "RPP25, BARD1, BRCA1, CD3EAP, CSTF2, DARS2 and DNMT3B was up-regulated in most of cervical cancer tissues compared with corresponding normal cervix tissues." (PMID 34863153, 2021). "Half of the BARD1 mutation carriers were found to have TNBC and were likely to have familial aggregation of liver, prostate, and cervical cancers compared to patients who tested negative for mutations in the 30 gene panel." (PMID 40805222, 2025). "BARD1 carriers had significant family histories of liver, prostate, and cervical cancers compared to non-carriers (p-values = 0.04, 0.018, and 0.037, respectively)." (PMID 40805222, 2025).
colorectal cancer (6 papers, 2020 to 2025). A primary or metastatic malignant neoplasm that affects the colon or rectum. "The second most abundant genus Corynebacterium was linked to the SNP rs117538984 located in the intronic region of BARD1 (p = 1.44 × 10−9), which was associated with colorectal cancer (p = 0.002) and pulmonary tuberculosis (p = 0.01) in the BBJ." (PMID 38291185, 2024). "Recent studies have also shown that BARD1 variants may play a role in colorectal cancer in families with a history of the disease." (PMID 40869938, 2025).
Ewing sarcoma (6 papers, 2020 to 2024). A small round cell tumor that lacks morphologic, immunohistochemical, and electron microscopic evidence of neuroectodermal differentiation. "Their study revealed that the loss of BARD1 increases Ewing sarcoma sensitivity to DNA damage, with Guanylate-binding protein 1 playing a role in the DNA damage response within Ewing sarcoma organoids." (PMID 37686615, 2023). "While any single germline DNA damage repair gene variant in patients with Ewing sarcoma is rare, as highlighted by our analysis of BARD1 germline variants in the PEDS MiONCOseq and St." (PMID 36187937, 2022). "We thus questioned the impact of BARD1 loss on Ewing cell sensitivity to DNA damage and the Ewing sarcoma transcriptome." (PMID 36187937, 2022). "Our index case of the first report of a patient with Ewing sarcoma and a germline pathogenic variant in BARD1 is listed in the footnote (a) for reference." (PMID 36187937, 2022). "Together, our findings demonstrate the impact of loss-of function mutations in DNA damage repair genes, such as BARD1, on Ewing sarcoma treatment response." (PMID 36187937, 2022). "We recently reported our discovery of a germline mutation in the DNA damage repair protein BARD1 (BRCA1-associated RING domain-1) in a patient with Ewing sarcoma." (PMID 36187937, 2022). "Having determined that Ewing sarcoma cells deficient in BARD1 demonstrate enhanced susceptibility to DNA damage, we next wanted to better understand the changes that occurred in the Ewing sarcoma cell transcriptome upon reducing BARD1 expression." (PMID 36187937, 2022). "We conclude that loss of BARD1 expression is only one of many possible factors contributing to GBP1 expression in Ewing sarcoma." (PMID 36187937, 2022). "This work provides preclinical support for the inclusion of pediatric patients with advanced Ewing sarcoma and pathogenic germline variants in BARD1 in future clinical trials testing novel agents inducing DNA damage/targeting DNA damage repair." (PMID 36187937, 2022). "We recently contributed to this growing body of literature by reporting our discovery of a paternally inherited germline frameshift pathogenic variant in the RING domain of BARD1 (BRCA1-associated RING domain protein 1) in a patient with Ewing sarcoma." (PMID 36187937, 2022). "Using the validated PSaRC318 Ewing sarcoma cell line as a tool, we next sought to address the impact of BARD1 loss on Ewing cell sensitivity to DNA damage." (PMID 36187937, 2022). "It is unknown whether the presence of a germline pathogenic variant in a DNA damage repair gene such as BARD1 is able to further disrupt DNA damage repair and enhance sensitivity of Ewing tumor cells to DNA-damaging agents." (PMID 36187937, 2022). "The contribution of germline pathogenic variants in DNA damage repair genes, such as BARD1, to the overall sensitivity of Ewing tumors to DNA damage is largely unknown." (PMID 36187937, 2022). "Thus, we questioned whether the subset of patients with Ewing sarcoma who also harbor germline pathogenic variants in DNA damage repair genes, such as a germline BARD1 mutation, may demonstrate enhanced sensitivity to PARPi/DNA-damaging agent combinations." (PMID 36187937, 2022). "To do this, we utilized an unbiased approach by performing RNA-seq analysis on RNA isolated from A673 Ewing sarcoma cells treated with control or BARD1 siRNA for 72 hours." (PMID 36187937, 2022). "Together, these data demonstrate that reduction of BARD1 in Ewing sarcoma: (i) enhances sensitivity to both talazoparib and niraparib, (ii) leads to increased apoptosis in the setting of PARPi plus direct DNA damage (radiation)." (PMID 36187937, 2022). "The interaction of the major oncogenic driver, EWS-FLI1, with the C-terminus of BARD1 as well as a frameshift deletion in the BRCA1-binding region of BARD1 in Ewing sarcoma strongly support the need for more functional studies of impaired DDR in Ewing sarcoma." (PMID 32708251, 2020).
Ewing sarcoma (continued). "Recently, the first germline variation in the BARD1 gene was identified in a patient with relapsed Ewing sarcoma." (PMID 32708251, 2020). "Of the priority candidates, 6 were found with enriched dependency in Ewing Sarcoma cell lines (AKT1, BARD1, HSP90AA1, NCOA1, SETDB1, SMAD4)." (PMID 38177639, 2024). "In comparison with other Ewing sarcoma cell lines (A673, TC71, CHLA9, and CHLA10), PSaRC318 cells demonstrate significantly less BARD1 expression upon densitometry analysis (P < 0.05)." (PMID 36187937, 2022). "We found that guanylate-binding protein 1 (GBP1) is significantly upregulated upon BARD1 downregulation and we subsequently demonstrate a role for GBP1 in DNA damage sensitivity in Ewing sarcoma." (PMID 36187937, 2022).
hepatocellular carcinoma (6 papers, 2017 to 2025). A malignant tumor that arises from hepatocytes. "The present study was designed to investigate the potential clinical, pathological, prognostic value, role and mechanism of BRCA1-associated RING Domain 1 (BARD1) in Hepatocellular carcinoma (HCC)." (PMID 28794477, 2017). "Upregulation of the cytoplasmic expression of BARD1 has been found in breast, ovarian, non-small cell lung, and hepatocellular cancers." (PMID 35406624, 2022). "BARD1 mutation is reported in 1.1% of hepatocellular adenomas, SGK1 mutation is observed in numerous tumor types, and TERT is also one of the most commonly mutated genes in hepatocellular carcinoma, with mutations predominantly in the reporter region that regulates gene expression, as in this case." (PMID 38903310, 2024).